LGMN (legumain)
Diseases named in the same sentence as LGMN in open-access papers (continued):
Sharing a sentence is not in itself a finding about the gene and the disease.
COVID-19 (4 papers, 2023 to 2025). A disease caused by infection with severe acute respiratory syndrome coronavirus 2. "Moreover, using data from patients with healthy, moderate, or severe disease we observed that LGMN expression was positively correlated with COVID-19 disease severity." (PMID 40674406, 2025). "Macrophages from patients with IPF and COVID-19 were both found to express fibrosis-associated genes including Secreted Phosphoprotein 1 (SPP1), transforming growth factor beta 1 (TGFB1), transforming growth factor beta-induced (TGFBI), legumain (LGMN), and C-C Motif Chemokine Ligand 18 (CCL18)." (PMID 37759460, 2023).
pancreatic cancer (4 papers, 2021 to 2024). "Moreover, knocking down of ELK1 reduced pancreatic cancer cells proliferation, invasion and survival, while LGMN restored the malignancy of pancreatic cancer in vitro and in vivo." (PMID 34966781, 2021). "We then analyzed the expression of ELK1 and LGMN in four different pancreatic cancer cell lines." (PMID 34966781, 2021). "We previously found that high expression of LGMN is involved in the progression of pancreatic carcinoma in an exosome-dependent manner and that LGMN independently indicated poor prognosis; however, the upstream regulation of LGMN remains unknown." (PMID 34966781, 2021). "Although we previously found that high LGMN expression was involved in the progression of pancreatic carcinoma in an exosome-dependent manner and LGMN could independently indicate poor prognosis, the upstream regulation of LGMN remains unknown." (PMID 34966781, 2021).
Parkinson disease (4 papers, 2019 to 2025). A progressive degenerative disorder of the central nervous system characterized by loss of dopamine producing neurons in the substantia nigra and the presence of Lewy bodies in the substantia nigra and locus coeruleus. "Legumain has been proposed as a novel therapeutic target for the treatment of neurodegenerative diseases such as Alzheimer’s and Parkinson’s disease, osteoporosis, and different cancers." (PMID 36555634, 2022). "Pathway analysis also highlighted that legumain protease activity corresponds to cell junction regulation and neurodegenerative pathways, which correlates with its known contribution to pathologies such as Alzheimer's and Parkinson's disease." (PMID 40970443, 2025). "Legumain has been suggested to also have a key role in the pathogenesis of Parkinson’s disease (PD) due to the cleavage of α-synuclein, triggering the aggregation of the cleavage products in Lewy bodies, the neurotoxicity of dopaminergic neurons, and movement disorders." (PMID 36555634, 2022).
pulmonary fibrosis (4 papers, 2022 to 2026). Chronic progressive interstitial lung disorder characterized by the replacement of the lung tissue by connective tissue, leading to progressive dyspnea, respiratory failure, or right heart failure. "Other important mediators associated with lung fibrosis are legumain, osteopontin, IL-4, IL-6, IL-13, IL-17, TNF-α, Gal-1, Gal-3, PDGF, and FGFR-1." (PMID 38540252, 2024). "The pathogenesis of pulmonary fibrosis involves various mediators such as TGF-β, legumain, osteopontin, IL-4, IL-6, IL-13, IL-17, TNF-α, Gal-1, Gal-3, PDGF, and FGFR-1." (PMID 38540252, 2024).
breast tumor (3 papers, 2017 to 2022). "Using a DNA-based vaccine against legumain as a tool, mice were immunized against legumain, leading to depletion of TAM in tumor tissues of 4T1 breast tumor-bearing mice." (PMID 28471401, 2017). "Legumain is an ideal target because it is highly expressed in M2-like TAMs in murine breast tumor tissues, whereas M1-like TAMs do not express legumain." (PMID 28467800, 2017).
gastric tumor (3 papers, 2020 to 2023). "In conclusion, the current study suggests that LGMN in TAMs performs a novel oncogenic role in the regulation of gastric tumor cell proliferation and invasion in vitro and in vivo." (PMID 31892854, 2020). "Similarly, in gastric tumors, the vesicular positivity of legumain was found in the cytoplasm of these neoplasms, whereas diffusely positive staining patterns were displayed in the normal mucosa tissues." (PMID 35203212, 2022).
glioma (3 papers, 2019 to 2022). A benign or malignant brain and spinal cord tumor that arises from glial cells (astrocytes, oligodendrocytes, ependymal cells). "In the examination of the normal tissues and a variety of tumor tissue, legumain had a low expression in normal tissue; the high expression was detected in many solid tumors, including breast, colon, lung, prostate, and ovarian tumors and malignant tumors of the central nervous system." (PMID 35399931, 2022).
oral cancer (3 papers, 2022 to 2025). "Legumain‐deficient mice were protected from oral cancer‐induced pain, and a legumain inhibitor exhibited analgesic effects." (PMID 39392222, 2025). "Oral cancers secrete proteases that activate PAR2, including legumain." (PMID 35260737, 2022).
renal fibrosis (3 papers, 2022). A final common manifestation of a wide variety of chronic kidney diseases characterized by glomerulosclerosis and tubulointerstitial fibrosis. "In this study, we identified loss of legumain promotes aging‐related renal fibrosis by accelerating tubular cell senescence and consequent activation of fibroblasts." (PMID 35195326, 2022). "Additionally, the loss of legumain mediates renal fibrosis as legumain deficiency induces premature senescence and the secretion of profibrotic cytokines during age-related renal fibrotic injury." (PMID 36555634, 2022). "Our previous data showed that deletion of legumain aggravates renal fibrosis in the mouse model of unilateral ureteral obstruction." (PMID 35195326, 2022). "To evaluate the effect of downregulation of legumain on renal fibrosis, we used a non‐contact coculture system of HK‐2 cells and BJ fibroblasts." (PMID 35195326, 2022). "Depletion of legumain accelerates premature senescence and promotes aging‐related renal fibrosis." (PMID 35195326, 2022).
Splenomegaly (3 papers, 2018 to 2025). Abnormal increased size of the spleen. "Legumain‐deficient mice have been previously reported to exhibit splenomegaly with increased neutrophil numbers in both peripheral blood and spleen, and this was in line with increased abundance of neutrophil‐associated proteins measured by quantitative proteomics." (PMID 39392222, 2025).
viral infection (3 papers, 2020 to 2025). "We found that loss of KCNA6 or LGMN significantly decreased viral infection by replication competent SARS-CoV-2." (PMID 40674406, 2025). "To examine the role LGMN’s cellular localization plays in viral infection we created LGMN signal peptide (SP) mutants." (PMID 40674406, 2025). "In orthogonal experiments, we show that disruption of endogenous LGMN or KCNA6 decreases viral infection and that inhibitors of candidate factors can reduce viral entry." (PMID 40674406, 2025). "In a complementary assay using replicating Spike-pseudotyped VSV with time-lapse imaging of virus infection, we found that two of the strongest hits validated by the pseudotyped lentiviral experiments, KCNA6 and LGMN, were able to similarly promote infection." (PMID 40674406, 2025). "TLR7 and 9 are legumain substrates, and thus legumain is involved in diverse functions of the immune system that are dependent on TLR7 and/or 9 signaling, including the immune response to various viral infections." (PMID 36555634, 2022). "Using a monoclonal 293T cell line with ACE2 genetically disrupted (hereafter ACE2KO 293T), we found that overexpression of ACE2 could induce viral infection, but overexpression of either KCNA6 or LGMN in this context did not promote entry by SARS-CoV-2 live virus over background levels." (PMID 40674406, 2025).
cervical cancer (2 papers, 2023 to 2024). A primary or metastatic malignant neoplasm involving the cervix. "It has been reported that the knockdown of LGMN in cervical cancer cell lines resulted in the reduction of cell migration/invasion mediated by MMPs." (PMID 38139241, 2023).
chronic pancreatitis (2 papers, 2022 to 2025). A chronic inflammatory process causing damage and fibrosis of the pancreatic parenchyma. "In chronic pancreatitis models, it has recently been demonstrated that macrophage‐derived legumain contributes to fibrosis associated with prolonged inflammation, and it may promote the transition to pancreatic adenocarcinoma." (PMID 39392222, 2025). "In contrast, legumain is shown to promote fibrogenesis in chronic pancreatitis, and it is suggested that macrophage M2-derived legumain mediates activation of pancreatic stellate cells and increases the synthesis of ECM proteins via the activation of TGF-β1." (PMID 36555634, 2022).
colitis (2 papers, 2025). Inflammation of the colon. "Of the WT‐enriched proteins, three were also enriched in naïve colons, including Cpt1b, Med6, and Serpina1d, while the remaining 34 upregulated proteins were only significant in the inflamed colon and may represent proteins affected by the increased legumain activity associated with colitis." (PMID 40970443, 2025). "Increased legumain activity was observed in acute colitis induced by TNBS, although it was most active in the distal region as opposed to the proximal region, which is in line with locations affected by these models." (PMID 39392222, 2025). "Together, these results suggest that legumain is activated in multiple models of acute experimental colitis." (PMID 39392222, 2025). "Using the activity‐based probe, LE28, we demonstrated that the cysteine protease legumain is activated in murine colon during acute experimental colitis induced by DSS or TNBS." (PMID 39392222, 2025). "Using a legumain‐selective activity‐based probe, LE28, we report that legumain is activated within colonocytes and macrophages of the murine colon, and that it is upregulated in models of acute experimental colitis." (PMID 39392222, 2025). "Collectively, these results demonstrate that legumain is dispensable for the initiation of symptoms associated with DSS‐induced acute colitis and does not significantly contribute to visceral hypersensitivity." (PMID 39392222, 2025). "In summary, we have identified that legumain is activated in the colon during experimental colitis." (PMID 39392222, 2025). "Loss of legumain activity, either through pharmacological inhibition or genetic deletion, was not protective against symptoms of colitis, suggesting it is dispensable for initiation of pathogenesis." (PMID 39392222, 2025). "Since we observed increased legumain expression in response to LI‐1 treatment, there may have been residual legumain activity over the course of colitis induction." (PMID 39392222, 2025). "Legumain is significantly upregulated in models of acute experimental colitis." (PMID 39392222, 2025). "Having demonstrated that legumain activity is upregulated in models of acute colitis, we next queried whether pharmacological blockade of its activity would alter the course of disease progression." (PMID 39392222, 2025). "We concluded that despite its activation, legumain does not significantly contribute to symptoms associated with acute colitis, given genetic or pharmacological loss of legumain activity did not noticeably alter DSS‐induced pathogenesis." (PMID 39392222, 2025). "Overall, the naïve legumain‐deficient mice exhibited less overall activity at baseline, but this was not dependent on colitis induction, suggesting that legumain does not significantly contribute to behaviors associated with colitis." (PMID 39392222, 2025). "Overall, these data shed light on the proteolytic contribution of legumain to normal colon function, and how dysregulation of legumain protease activity may contribute to DSS‐induced colitis in mice." (PMID 40970443, 2025). "While the impact of Ppp1r1b cleavage in the gut is unknown, it is possible that legumain‐mediated cleavage of Pppr1r1b contributes to colitis pathogenesis." (PMID 40970443, 2025). "In addition to DSS, we also examined legumain in TNBS‐induced colitis." (PMID 39392222, 2025). "Mice were treated daily with the covalent legumain inhibitor LI‐1, which is an analogue of SD‐134 that is acetylated instead of Cbz‐capped or DMSO vehicle during colitis induction with DSS." (PMID 39392222, 2025). "Moreover, legumain inhibition or deletion had no obvious impacts on symptoms or histological features associated with dextran sulfate sodium‐induced colitis, suggesting its proteolytic activity is dispensable for colitis initiation." (PMID 39392222, 2025).
colitis (continued). "Although we did not observe overt phenotypic differences in legumain‐deficient mice during acute colitis, we queried whether we could obtain information about its potential roles in healthy and inflamed gut and examine broad changes in proteolysis that are associated with colitis." (PMID 39392222, 2025). "Legumain‐deficient mice, however, were not protected from this symptom in DSS‐induced colitis." (PMID 39392222, 2025).
diabetes (2 papers, 2021 to 2022). "Further studies revealing the immanent connection of legumain with the pathology of diabetes-associated PAD may confirm the predictive value of serum legumain for PAD and provide a new strategy for PAD." (PMID 34961842, 2021).
influenza (2 papers, 2015 to 2022). An acute viral infection of the respiratory tract, occurring in isolated cases, in epidemics, or in pandemics; it is caused by serologically different strains of viruses (influenzaviruses) designated A, B, and C, has a 3-day incubation period, and usually lasts for 3 to 10 days. "Notably, a number of proteins lacking a signal peptide and not annotated as ‘secreted’ elsewhere were overrepresented in the influenza stimulated group, including the proteases cathepsin c, cathepsin z, legumain, and the transcription factor IRF8." (PMID 35401570, 2022).
lymph node metastasis (2 papers, 2013 to 2015). "Over-expression of Legumain was significantly associated with lymph node metastasis (P<0.001), peritoneal metastasis (P = 0.002), hepatic metastasis (P = 0.014) and histologic type (P = 0.095), the T stage (P = 0.003)." (PMID 24023813, 2013). "In our study, we showed a significant correlation between elevated Legumain expression and T stage (P = 0.003), lymph node metastasis (P<0.001), peritoneal metastasis (P = 0.002) and hepatic metastasis (P = 0.014)." (PMID 24023813, 2013). "Expression of Legumain in normal colonic mucosa, cancerous tissue and lymph node metastasis." (PMID 24023813, 2013). "Our meta-analysis demonstrated that LGMN overexpression was not related to tumor differentiation or to lymph node metastasis." (PMID 26607955, 2015).
lysosomal storage disease (2 papers, 2018 to 2024). A metabolic disorder caused by mutations in proteins critical for lysosomal function, including lysosomal enzymes, lysosomal integral membrane proteins, and proteins involved in the post-translational modification and trafficking of lysosomal proteins. "Legumain contributes to renal homeostasis and lysosomal protein turnover, as evidenced by renal insufficiency and lysosomal storage disorders in legumain-deficient mice." (PMID 38199506, 2024). "As with previous studies, this may suggest compensation for loss of lysosomal hydrolase activity in legumain-deficient samples, which may contribute to lysosomal storage disorders." (PMID 38199506, 2024).
osteosarcoma (2 papers, 2023 to 2024). A usually aggressive malignant bone-forming mesenchymal neoplasm, predominantly affecting adolescents and young adults. "The value of 0.799 obtained from the area under the curve (AUC) indicated that LGMN expression exhibited an excellent diagnostic value for osteosarcoma." (PMID 38980440, 2024). "The present study also suggested that it is highly likely that LGMN expression might be used as a biomarker if LGMN expressed highly in osteosarcoma and tumor-associated macrophages (TAMs)." (PMID 38980440, 2024). "This study was also designed to validate the hypothesis that LGMN might work as a potential diagnostic and prognostic biomarker and/or therapeutic target of osteosarcoma." (PMID 38980440, 2024). "Our investigation reinforces the pivotal role of LGMN as a prognostic indicator in osteosarcoma, shedding light on its integral function in modulating the tumor's immune landscape." (PMID 38980440, 2024). "To further analyze effect of LGMN expression on the prognosis of osteosarcoma, we employed a survival package to compare the prognosis of the validation sets in terms of overall survival (OS), progression-free survival (PFS) and time to progression (TTP)." (PMID 38980440, 2024). "Based on the expression levels of the target gene LGMN in the OS samples from the TCGA-OS dataset, consensus clustering analysis was employed to identify distinct cancer subtypes related to osteosarcoma." (PMID 38980440, 2024). "In this study, we have investigated LGMN expression in osteosarcoma and normal tissues based on the GEO and the database." (PMID 38980440, 2024). "Our study underscores the prognostic value of LGMN in osteosarcoma and its potential as a therapeutic target." (PMID 38980440, 2024). "Against this background, the present study has been conducted to investigate the potential prognostic value of LGMN expression for osteosarcoma." (PMID 38980440, 2024). "Using the GSE42352 dataset, we found significant differences in LGMN expression between osteosarcoma and the normal samples." (PMID 38980440, 2024). "In this study, we have performed a comprehensive analysis of the microarray datasets and discovered that LGMN expression could increase the incidence of osteosarcoma by potentiating pathways." (PMID 38980440, 2024). "In this study, the results of GO, KEGG and GSEA enrichment analyses suggested that the development of osteosarcoma, infection immunity and high LGMN expression might be related to cancer and immune microenvironment." (PMID 38980440, 2024). "Of particular importance, the differential expression of LGMN observed between these subtypes implies its potential as a biomarker for subgroup differentiation, thereby furnishing a robust molecular basis for the implementation of personalized medicine strategies in osteosarcoma." (PMID 38980440, 2024).
ovarian tumors (2 papers, 2022 to 2025). "In addition, higher legumain expression increases the degree of malignancy in malignant human ovarian tumours." (PMID 40027188, 2025).
rectal cancer (2 papers, 2015 to 2024). A primary or metastatic malignant neoplasm that affects the rectum. "TCGA data showed that among patients with rectal cancer, the LGMNHigh group had significantly shorter survival than the LGMNLow group (P < 0.05), further supporting the associations between high legumain expression, tumor progression, and poor prognosis." (PMID 26607955, 2015). "For example, in patients with rectal cancer, cases with overexpressed LGMN displayed lower overall survival rate than cases with low LGMN expression." (PMID 38980440, 2024). "Furthermore, Cancer Genome Atlas data showed that among patients with rectal cancer, those with tumors overexpressing legumain had shorter overall survival than those in the low expression group (P < 0.05)." (PMID 26607955, 2015).
renal cell carcinoma (2 papers, 2025). "We also disrupted the same three genes in the renal cell carcinoma line SW156, which expresses moderate levels of ACE2 and LGMN, but low to almost undetectable levels of TMPRSS2 and serves as a model for SARS-CoV-2 infection of the kidney." (PMID 40674406, 2025).
acute lymphoblastic leukemia (1 paper, 2025). Leukemia with an acute onset, characterized by the presence of lymphoblasts in the bone marrow and the peripheral blood. "We selected the T-cell acute lymphoblastic leukemia cell line Loucy as it expresses moderate levels of endogenous KCNA6 and LGMN, low levels of TMPRSS2, and low to undetectable levels of ACE2." (PMID 40674406, 2025).